RNU6-195P (RNA, U6 small nuclear 195, pseudogene)
Gene: Small nuclear RNA gene on chromosome 19 (40,708,055 to 40,708,163, reverse strand). Ensembl gene ENSG00000223284.
Homologues: Orthologues: chimpanzee U6 (99% identical), macaque U6 (91% identical), rat LOC120103234 (66% identical), mouse Gm56147 (61% identical). Paralogues in human: RNU6-1309P (82% identical), RNU6-270P (80% identical), RNU6-727P (80% identical), RNU6-1113P (79% identical), RNU6-1340P (79% identical), RNU6-24P (79% identical), RNU6-742P (79% identical), RNU6-774P (79% identical), RNU6-834P (79% identical), RNU6-1209P (78% identical), RNU6-543P (78% identical), RNU6-560P (78% identical), and 1286 more.